CRP (C-reactive protein)
Diseases named in the same sentence as CRP in open-access papers (continued):
Sharing a sentence is not in itself a finding about the gene and the disease.
COVID-19 (continued). "Based on multivariate analyses, decreased apoA-1 and HDL-C levels were independently associated with COVID-19 severity after adjusting for established indicators of severity, such as age, low albumin, and increased D-dimer, CRP, and IL-6 levels." (PMID 33344516, 2020). "Compared to other routine laboratory parameters, we found that CRP level was significantly associated with COVID-19 severity." (PMID 33312067, 2020). "In patients infected with COVID-19, the presence of increased levels of serum inflammatory markers including IL-6, CRP, LDH, ferritin, and D-dimers has been associated with an increased risk of progression to more severe forms of the disease." (PMID 33133323, 2020). "It has been demonstrated that elevated serum levels of IL-6 and CRP as inflammatory markers are associated with the severity of COVID-19 and can be used as a predictive factor for disease risk." (PMID 32943404, 2020). "Prior research suggests that patients with COVID-19 who had an older age, lymphopenia, elevated CRP or comorbidity are at higher risk for adverse outcome and death." (PMID 33353548, 2020). "Laboratory biomarkers reportedly associated with COVID-19 pathophysiology include lymphocytes, CRP, D-dimer, PCT, troponins, ferritin, and IL-6, among others." (PMID 32727345, 2020). "Apart from the risk factors above, patient age, white blood cell count, neutrophil count, serum AST, ALT, LDH, Urea, CRP, and D-dimer level were all associated with the severity of COVID-19 patients." (PMID 32633729, 2020). "The results showed that the patient's age and CRP levels were independent risk factors for predicting death, i.e., age and CRP predicted the risk of death in patients with COVID-19." (PMID 32802219, 2020). "In summary, based on multiple risk factors (age, NLR, D-dimer and CRP), our nomogram for predicting the prognosis of patients with COVID-19 showed good discrimination and calibration." (PMID 32867787, 2020). "In patients with COVID-19, disease progression is significantly associated with older age and higher circulating levels of CRP, procalcitionin, IL-6, and lactate." (PMID 33239109, 2020). "The results of the multivariate logistic regression indicate that age, lymphocyte, and CRP are independent predictors for an increased risk of severe COVID-19." (PMID 32589691, 2020). "TL was significantly correlated to CRP and neutrophil-to-lymphocyte ratio, both factors previously associated with poorer COVID-19 outcome." (PMID 33104521, 2020). "Based on this analysis of the primary COVID-19 data, elevated levels of CRP, TNF-α, and IL-6 were found to be associated with increased odds of the severe form of COVID-19 that can result in liver damage in these cases." (PMID 33244370, 2020). "In conclusion, this study showed that premorbid ADL impairment, fever during hospitalization, and initial CRP were associated with poor prognosis in elderly patients with COVID-19." (PMID 33291617, 2020). "Laboratory parameters such as neutrophil-to-lymphocyte ratio, C-reactive protein (CRP), interleukin (IL)-6 and dimer-D levels are reported as indicators of COVID-19 severity when associated to clinical features of the infection." (PMID 33178720, 2020). "While lymphocyte count was inversely associated with the death following COVID-19, creatinine and CRP level had direct association with it." (PMID 32641974, 2020). "While the link between diabetes and severe COVID-19 complications remains unclear, limited data suggest that markers such as interleukin (IL)-1, IL-6, C-reactive protein, and D-dimer are associated with COVID-19 severity in diabetic individuals." (PMID 40372276, 2025). "An association between HCoV co-infection and increased COVID-19 severity has been reported in hospitalized patients, characterized by longer hospital stays and critically elevated C-reactive protein (CRP) levels compared to patients infected only with SARS-CoV-2." (PMID 41439856, 2025).
COVID-19 (continued). "Moreover, higher levels of procalcitonin, ferritin, CRP, lactate dehydrogenase, interleukin-6, and D-dimer are linked to poor prognosis and high mortality risk for COVID-19 patients." (PMID 40766923, 2025). "Organ failure associated with the extrapulmonary manifestations of COVID-19 may be linked to laboratory markers of inflammation, such as elevated C-reactive protein levels." (PMID 40564052, 2025). "The sensitivity analysis adjusting for CRP and d-dimer in addition to the other covariates had fewer observations (N = 2,500) but showed similar relationships between LFTs or composite liver scores and risk of severe COVID-19." (PMID 41561952, 2025). "Although the cohort was small, the findings suggest that elevated CRP is not only a marker of disease severity but may also play a direct pathogenic role in COVID-19 progression." (PMID 41007829, 2025). "The risk of thrombotic complications in COVID-19 cases has been associated with various biomarkers related to inflammation, such as C-reactive protein (CRP), ferritin, D-dimer, lactate dehydrogenase (LDH), platelet-to-lymphocyte ratio (PLR), and neutrophil-to-lymphocyte ratio (NLR)." (PMID 41465785, 2025). "Early pandemic reports indicate that severe COVID-19 is often associated with impaired germinal center responses (e.g., low lymphocytes, poor antibody affinity maturation) alongside heightened innate activation (elevated CRP, monocyte subsets)." (PMID 40733727, 2025). "From the 3 patients that were hospitalized, 2 patients showed clinical and radiological signs of COVID-19-related pneumonia, one of which also showed signs of bacterial superinfection with strongly elevated levels of C-reactive protein." (PMID 40557056, 2025). "Higher leukocyte counts and increased CRP levels also have been associated with COVID-19 severity." (PMID 40592354, 2025). "The increase in NLR and hs-CRP are associated with the severity and mortality of COVID-19." (PMID 39940787, 2025). "Furthermore, in the same analysis, a statistically significant association was observed between CRP and COVID-19 + EBV coinfection (χ2 = 5.312, p = 0.021), and the Chi-square test indicated a direct, yet weak relationship (φ = 0.117)." (PMID 40427060, 2025). "A similar study found a strong association between COVID-19 severity and elevated levels of C-reactive protein (CRP), procalcitonin, interleukin-6, neutrophils, hs-troponin T, lactate dehydrogenase (LDH), ferritin and D-dimers, along with decreased levels of albumin, lymphocytes and platelets." (PMID 40283188, 2025). "Thus, CRP is considered an independent predictor of severe COVID-19, consistent with our finding of a significant association between CRP and disease severity." (PMID 39518479, 2024). "Also, systemic CRP and ferritin levels showed a significant positive association with severity and were independent predictors of survival in COVID-19 patients." (PMID 38183501, 2024). "The main objective was to evaluate the distribution of mortality between sepsis and septic shock patients and identify contributing factors (e.g., serum lactate, lactate/albumin ratio, C-reactive protein, and platelet levels) associated with 30-day mortality among COVID-19 patients." (PMID 38576552, 2024). "Moreover, the study by Wassan Nori highlighted the significant role of C-reactive protein (CRP) as a diagnostic and prognostic biomarker in assessing the risk of mortality among elderly COVID-19 patients." (PMID 39685051, 2024). "In this study, the decrease in C-reactive protein levels was significantly associated with successful extubation in mechanically ventilated COVID-19 patients, suggesting that this biomarker may contribute to decision-making in this context." (PMID 38597482, 2024).
COVID-19 (continued). "Multivariate analysis indicated that the age of patients (OR = 1.06; 95% CI, 1.04–1.08, < 0.001), D-dimer (OR = 1.40; 95% CI, 1.06–1.56, p = 0.002), and CRP levels on admission (OR = 1.12; 95% CI, 1.06–1.26, p = 0.003) were risk factors associated with severe COVID-19." (PMID 38783290, 2024). "In addition to DNA damage, severe COVID-19 is associated with age, C-reactive protein (CRP), and creatinine." (PMID 39408623, 2024). "Increased C-reactive protein, combined with increased serum lactate and a high lactate/albumin ratio, may assist clinicians in identifying COVID-19 patients at risk of mechanical ventilation and mortality upon admission." (PMID 38576552, 2024). "In conclusion, polymorphisms within the CRP gene may relate to serum CRP levels and mortality among COVID-19 patients." (PMID 38184750, 2024). "In the present study, we aimed to quantify the circulating levels of novel serum biomarkers including GDF-15, PIVKA-II, sdLDL, suPAR, and of CRP in hospitalized COVID-19 patients compared with healthy subjects and to evaluate their association(s) with outcomes in COVID-19." (PMID 38700782, 2024). "In addition, a study showed that elevated serum IL-6 and CRP levels were closely associated with the severity of pneumonia in COVID-19 patients." (PMID 39337223, 2024). "The study did show a possible protective impact associated with the use of ACEi/ARBs in COVID-19 based on the reduction in C-reactive protein (CRP) and D-dimer in these groups when compared to control groups, but the study suggested that larger sample numbers are required to confirm this effect." (PMID 38576704, 2024). "However, in multivariable analysis, only older age, male gender, presence of comorbidities, and a high CRP were considered as risk predictors of COVID-19 severe cases." (PMID 38263160, 2024). "Previous studies demonstrated that severe COVID-19 was associated with higher CRP levels in adults." (PMID 38849648, 2024). "While our study focused on the association between platelet activation and psychiatric disorders, the lack of significant associations with other markers of inflammation, such as CRP, suggests a unique relationship between platelet activation and psychiatric outcomes in the context of COVID-19." (PMID 38997256, 2024). "This study examined whether CRP rs1205 and rs1800947 polymorphisms were associated with COVID-19 mortality among various severe acute respiratory syndrome Coronavirus 2 (SARS-CoV-2) variants." (PMID 38184750, 2024). "In addition to the increased mortality data we provide here, CRP levels are associated with venous thromboembolic disease in COVID-19 with the worst outcomes seen in patients with high CRP and D-dimer concentrations." (PMID 39009040, 2024). "Multivariate analysis indicated that increased C-reactive protein (CRP) levels and lower microbiome diversity were significantly associated with severe COVID-19 (aOR = 2.8S, 95% CI 1.09–7.41), while risk of severe disease progression was shown in terms of Shannon diversity index < 2.25 (p = 0.032)." (PMID 38257958, 2024). "Indeed, in one study, it was found that significant elevation in the abundance of CRP in hospitalized COVID-19 patients is associated with QTc interval prolongation, increasing thus the risk of ventricular arrythmias and sudden death." (PMID 39594201, 2024). "Lastly, the mild form of COVID-19 experienced by these patients may explain the unclear association between CRP and imatinib Ctrough variation." (PMID 39445010, 2024). "Our study combined high CRP, high neutrophils, low lymphocytes, and low albumin as a group and defined a population at high risk of death, providing a new predictive strategy for COVID-19." (PMID 38698064, 2024). "CRP is an important component of the innate immune system, thus supporting a role of the gene and this variant’s potential effects on the pathophysiology of COVID-19." (PMID 38662664, 2024).
COVID-19 (continued). "The blood markers most strongly associated with 28-day mortality in COVID-19 patients were lowest albumin level, peak neutrophil count, and peak CRP (p < 0.001), while the strongest markers for pneumonia patients were lowest albumin level and age on admission (p = 0.043 and p = 0.001 respectively)." (PMID 39266635, 2024). "A retrospective study involving 576 patients found that those with anosmia had higher levels of lymphocytes, haemoglobin, and GFR, and lower levels of D-dimer and CRP, indicating a milder immune and inflammatory response to SARS-CoV-2 infection." (PMID 38272920, 2024). "Additionally, in COVID-19 patients, factors such as lymphopenia, thrombocytopenia, elevated d-dimer levels, and high CRP are associated with a poor prognosis and increased mortality." (PMID 38433274, 2024). "Additionally, it was found that elevated CRP levels are associated with an increased risk of mortality in COVID-19 patients, with an optimal cutoff value of ≥40 mg/L." (PMID 39458141, 2024). "In this sense, the development of AKI in patients with COVID-19 has been associated with different variables, including smoking, increased levels of C-reactive protein (CRP), the extent of lung involvement, high leukocyte count, and the requirement for mechanical ventilation." (PMID 38804444, 2024). "Some studies suggest that high levels of D-dimer, C-reactive protein, and the presence of lymphopenia may be associated with an increased susceptibility to develop post-COVID-19 symptoms." (PMID 39772122, 2024). "In addition to troponin levels, which were elevated in all patients with COVID-19, additional clinical biomarkers that were associated with poor outcomes included NT-proBNP and C-Reactive Protein levels." (PMID 39197405, 2024). "The study authors found that angiotensin receptor blocker use was associated with a significantly improved COVID-19 outcome, in part due to lower circulating levels of mortality-predicting markers, including leukocytes, neutrophils, C-reactive protein, procalcitonin, and IL-6." (PMID 39518552, 2024). "Thus, we aimed to contemplate the CRP, ferritin, and D-dimer values and to determine their association with COVID-19 severity in the Qunfudhah region." (PMID 38610151, 2024). "Canakinumab, a human monoclonal antibody targeting IL-1β, is associated with the reduction of serum C-reactive protein level and the improvement of overall mortality in COVID-19; case reports showed that canakinumab can reduce the risk of recurrence of systemic disease-related pericarditis." (PMID 38455049, 2024). "The overproduction of inflammatory cytokines in COVID-19 patients with severe disease may cause high CRP values." (PMID 38741671, 2024). "Similarly, within the moderate COVID-19 cohort, there was a positive association between serum adiponectin and CRP levels." (PMID 38791005, 2024). "C-reactive protein (CRP), white cell count, and cytokines (CK) such as interleukin-6 (IL-6), IL-8, and IL-10 have been investigated as factors associated with the diagnosis or severity of COVID-19." (PMID 39654974, 2024). "Another risk score incorporated oxygen saturation, CRP > 73:1 mg/L, increased prothrombin time (16.2 s), diastolic blood pressure ≤ 75 mmHg, lactate dehydrogenase, and blood urea nitrogen > 23 mg/dL as primary risk factors for hospital mortality of COVID-19." (PMID 38391586, 2024). "The research conducted by Matteo Luigi Giuseppe Leoni indicates that the prevalence of malnutrition is high among critically ill COVID-19 patients admitted to the ICU, and that mNUTRIC and CRP levels are independently associated with 28-day mortality in critically ill COVID-19 patients." (PMID 39668901, 2024). "COVID-19 death rates were significantly higher in patients with the CRP rs1205 T allele." (PMID 38184750, 2024). "Furthermore, evidence suggests that elevated serum CRP levels, procalcitonin levels, and neutrophil counts, along with decreased lymphocyte counts, are associated with severe COVID-19 outcomes." (PMID 39685844, 2024).
COVID-19 (continued). "In addition, persistent fever, elevated levels of CRP, interleukin-6, and procalcitonin led us to consider a potential association with COVID-19-related MIS in adults, where IBD was the predominant presentation." (PMID 38669420, 2024). "Severe COVID-19 is characterised by marked inflammation of the lungs, which causes respiratory failure and is usually associated with elevated circulating inflammatory markers such as C-reactive protein (CRP), interleukin 1β (IL-1β), and IL-61–4." (PMID 38296965, 2024). "In COVID-19, IL-6, CRP, and LPS levels are elevated and associated with adverse clinical outcomes." (PMID 37238973, 2023). "Elevated C-reactive protein (CRP) levels have been associated with poorer COVID-19 outcomes." (PMID 38003780, 2023). "Therefore, measuring the levels of IL-6, IL-12p70, CRP, and D-dimer at presentation can predict the risk of disease progression in COVID-19 patients." (PMID 37228441, 2023). "Within the analyzed cohort of critically ill COVID-19 patients, a persistent pro-inflammatory profile characterized by persistently elevated serum CRP levels over time was associated with a risk of developing an infection during the ICU stay, as delineated by Patterns A and B." (PMID 37834754, 2023). "Several studies that investigated prediction risk scores for ventilation in patients with COVID-19 revealed that CRP could predict the need for ventilation in these patients." (PMID 37217858, 2023). "Accuracy of the predictions made by the corresponding ML tools fluctuates from 81 to 96%, including age, reduced oxygen saturation, increased serum lactate dehydrogenase, C-reactive protein, and impaired kidney function as major predictors of COVID-19-associated death." (PMID 36826535, 2023). "The survival of COVID-19 may be associated with persistent increases in CRP and D-dimer levels, indicating long-lasting inflammation in the body, even up to several months after combating the virus." (PMID 38002663, 2023). "CRP has been shown to be associated with the progression of COVID-19." (PMID 36986138, 2023). "CRP proved to be a useful early marker to predict the risk of severe disease and death as it is closely linked to cytokine production and tissue destruction in COVID-19 patients." (PMID 38274890, 2023). "Furthermore, obtaining daily CRP values for hospitalized COVID-19 patients can provide early thresholds and facilitate risk stratification and prognostication." (PMID 37720137, 2023). "Other biomarkers that have been associated with COVID-19 and cardiovascular complications include interleukin-6 (IL-6), C-reactive protein (CRP), and ferritin, which are markers of inflammation and have been linked to a hyperinflammatory response in severe COVID-19 cases." (PMID 37568870, 2023). "Importantly, the severe cases of COVID-19 investigated in the present study associated a major increase in the CRP and MCP-1 serum levels assisted by enhanced suPAR, sTREM-1 and HGF values." (PMID 37388734, 2023). "Moreover, elevated D-dimer, LDH, and CRP levels were associated with adverse side effects of COVID-19 including high risk of acute respiratory distress syndrome (ARDS), ICU admission, and mortality." (PMID 37199912, 2023). "Importantly, CRP has been associated with disease progression and is an early predictor for severe COVID-19." (PMID 37173883, 2023). "Elevated CRP levels were associated with COVID-19 severity (p=0.01)." (PMID 38268924, 2023). "The present study shows that the characteristics of CRP and lymphocytes extracted from blood tests can be used for a more accurate and early diagnosis of people with Covid‐19." (PMID 36620509, 2023). "Following adjustment for age, baseline CRP, ethnicity, steroid use, and COVID-19 variant, there was evidence that the effect of treatment with anti-IL-6 receptor monoclonal antibodies differs between males and females (p = 0.14), although this was not statistically significant." (PMID 37598275, 2023).